MAG (myelin associated glycoprotein)
Diseases named in the same sentence as MAG in open-access papers (continued):
Sharing a sentence is not in itself a finding about the gene and the disease.
polyneuropathy (28 papers, 2014 to 2025). A disease or disorder affecting more than one nerve. "Recently, ibrutinib has proven to be active in 3 MYD88L265P-mutated and CXCR4 wild-type patients with anti-MAG antibody polyneuropathy and WM." (PMID 35326711, 2022). "Demyelinating polyneuropathy in WM is commonly symmetric, distal, slowly progressive and associated with IgM antibodies against nerve antigens, most commonly MAG." (PMID 35326711, 2022). "Distal acquired demyelinating symmetric polyneuropathy (DADS) has the phenotype of a symmetric, demyelinating sensory, length-dependent polyneuropathy and is frequently associated with paraproteinemia and anti myelin associated glycoprotein (MAG) antibodies." (PMID 33790853, 2021). "In summary, the data presented here clearly show the heterogeneity of polyneuropathy associated with anti-MAG antibodies." (PMID 26065001, 2015). "The objective of this retrospective study was to reexamine the concept that polyneuropathy associated with anti-MAG antibodies is a homogeneous entity." (PMID 26065001, 2015). "It is also established that in the context of polyneuropathy, the monoclonal IgM of patients may target myelin-associated glycoprotein (MAG), chondroitin, or a ganglioside." (PMID 38022528, 2023). "Ibrutinib, a first-generation BTK inhibitor, has shown promise in improving anti-MAG antibody polyneuropathy." (PMID 40351903, 2025). "Despite being effective in less than half of patients with anti-MAG antibody polyneuropathy it seems to be the treatment of choice thanks to its safety and good tolerable profile." (PMID 37298132, 2023). "Two CLL patients with concurrent anti-MAG antibody polyneuropathy were treated with six cycles of chlorambucil–obinutuzumab, showing persistent hematological and neurological remissions." (PMID 35326711, 2022). "Despite being effective in less than half of patients with anti-MAG antibody polyneuropathy, in clinical practice it remains the treatment of choice, thanks to its favorable safety and tolerability profile." (PMID 35349079, 2022). "Polyneuropathy with IgM anti-MAG antibodies and IgM MGUS, but also WM, marginal zone lymphoma (MZL) or CLL is the most common IgM paraproteinemic polyneuropathy." (PMID 35326711, 2022). "Whatever the case, these two patients suggest that anti-MAG antibody polyneuropathy displays a spectrum of disease that includes patients that test negative for the presence of gammopathy." (PMID 30992531, 2019). "In this series, we have retrospectively reviewed clinical and laboratory findings from 60 patients with polyneuropathy, IgM gammopathy, and anti-MAG antibodies." (PMID 26065001, 2015). "More recent studies suggest that rituximab is effective but in no more than half of the patients with polyneuropathy associated with anti-MAG antibodies." (PMID 26065001, 2015). "Moreover, a recent work has shown that it is valid and robust in detecting anti-MAG antibodies in patients with IgM MG and polyneuropathy." (PMID 26065001, 2015). "Anti-MAG antibodies have also been observed in various polyneuropathies." (PMID 24988487, 2014). "We found that those classified as demyelinating had more lambda light chains (14 vs 5, p = 0.017), had all the anti-MAG antibody-positive patients (8 vs 0, p = 0.005) and had more severe polyneuropathy as shown by the VPT, TCNS data and the number of abnormal NCS parameters." (PMID 24801490, 2014). "The distal form of CIDP requires differentiation from axonal neuropathies (e.g., metabolic-diabetic neuropathy) genetic or anti-MAG IGM neuropathy, POEMS syndrome (Polyneuropathy, Organomegaly, Endocrinopathy, Monoclonal plasma cell disorder, Skin changes)." (PMID 37298132, 2023). "Indeed, as reviewed, immunomodulatory treatments like intravenous immunoglobulin (IVIg) have demonstrated a short term and modest effect on patients with polyneuropathy and anti-MAG antibodies and are not usually considered as a first-line treatment of this condition." (PMID 26065001, 2015).
chronic inflammatory demyelinating polyradiculoneuropathy (15 papers, 2015 to 2025). A rare neurological disorder in which there is inflammation of nerve roots and peripheral nerves and destruction of the fatty protective covering (myelin sheath) over the nerves. "Onion bulbs are typically observed in inherited neuropathies such as CMT1A, CMT1B, and Refsum’s disease, but also in chronic inflammatory demyelinating polyneuropathy (CIDP) and anti-myelin associated glycoprotein (MAG) neuropathy." (PMID 40244242, 2025). "Rituximab has proven to be effective in other monoclonal gammopathies by decreasing the antibodies causing the diseases, such as chronic inflammatory demyelinating polyradiculoneuropathy (CIDP), anti-MAG, or multifocal motor neuropathy (MMN)." (PMID 37337500, 2023).
schizophrenia (14 papers, 2007 to 2024). A major psychotic disorder characterized by abnormalities in the perception or expression of reality. "A DTI study found a relationship between variants of genes related to oligodendrocytes, e.g., myelin-associated glycoprotein, and the integrity of white matter tracts and cognition in patients with schizophrenia." (PMID 36291109, 2022). "For example, decreases in neocortical myelin development and myelin-related gene expression resulting in dysregulated CNP and myelin-associated protein (MAG) levels have been observed in patients with schizophrenia (SZ)." (PMID 34692694, 2021). "Genetic variants of SIGLEC3/CD33, SIGLEC11, and SIGLEC14 have been associated with neurodegenerative diseases such as Alzheimer’s disease, while sialyltransferase ST8SIA2 and SIGLEC4/MAG have been linked to psychiatric diseases such as schizophrenia, bipolar disorders, and autism spectrum disorders." (PMID 38529039, 2024). "Moreover, the down-regulation of MAG in the brain is associated with schizophrenia." (PMID 30893812, 2019). "Decreased transcript expression of Tf and MAG in the white matter of the ACC has been reported in subjects with schizophrenia." (PMID 32714147, 2020). "There are consistent reports of reduced expression of genes (MAG, MAL, MBP, PLP, MOG, NRG1, and Olig2, among others) associated with oligodendrocytes and myelin, and therefore involved in neuronal development or signal transmission in schizophrenia." (PMID 35326310, 2022). "Discrepancy was also seen in genetic association analyses; some, but not all, of the analyses, linked MAG gene to schizophrenia." (PMID 22937274, 2011). "The association of a myelination-related module with schizophrenia is in line with a wide range of reported white matter abnormalities linked to the illness and genetic studies that have contributed a number of myelin and oligodendrocyte –related genes as candidate genes (e.g. APOD, PLP1, MAG)." (PMID 24070017, 2013). "Genetic and neuroimaging data have shown that the MAG, Olig2, and CNP genes can influence white matter integrity and cognitive performance in schizophrenia patients." (PMID 32425837, 2020). "MAG, CNP, PLP1, and MBP were found reduced in mRNA samples from patients with schizophrenia in postmortem studies." (PMID 32425837, 2020). "Several of the upregulated genes (e.g. MAG, MAL and CNP) have previously been reported as downregulated in post-mortem brain samples from schizophrenia patients." (PMID 29187753, 2017). "While no direct link between schizophrenia and the CD33-related SIGLECs has been described so far, patient-specific polymorphisms in the SIGLEC4/MAG gene expressed in oligodendrocytes have been significantly associated with the disease." (PMID 38529039, 2024).
multiple sclerosis (12 papers, 2013 to 2025). A progressive autoimmune disorder affecting the central nervous system resulting in demyelination. "Due to obvious role of MAG in neuronal regeneration and multiple sclerosis there is a thrust to use it as a therapeutic target and GlaxoSmithKline has shown special interest in this molecule." (PMID 31546700, 2019). "MAG and dMAG are highly relevant in cases where myelin sheath is disrupted such as multiple sclerosis." (PMID 31546700, 2019). "Calpain-mediated downregulation of MAG has been found in demyelinating diseases, such as multiple sclerosis." (PMID 29467717, 2018). "Overall, MAG and other targets in the growth inhibitory signaling pathway show promise for translation to clinical study for treatment of various disorders, from multiple sclerosis and Alzheimer’s Disease to spinal cord injury." (PMID 26441514, 2015). "Western blotting analysis revealed significantly elevated protein expression of the pro-inflammatory cytokine TNF-α (a critical factor in multiple sclerosis with myelinolytic effects) and reduced expression of myelin-associated proteins MBP and MAG in Cuprizone-fed mice compared to controls." (PMID 40563355, 2025). "It was demonstrated that one of the most drastically reduced proteins in the brains of Gpr37/Gpr37L1 double knockout mice was the myelin-associated glycoprotein MAG, suggesting that GPR37 may be a potential drug target for the treatment of demyelinating diseases such as multiple sclerosis." (PMID 40822851, 2025). "Our study demonstrated an unexpected cross-talk between the environmental protein (ANGPTL2) and its surface receptor (MAG) in the regulation of oligodendrocyte differentiation, which may benefit the treatment of many demyelination disorders, including multiple sclerosis." (PMID 36855057, 2023). "This enhanced expression of MAG suggests improved myelin stability and function due to IMF, similar to previous findings in multiple sclerosis (MS) research." (PMID 39780365, 2025).
Alzheimer disease (9 papers, 2014 to 2024). A progressive, neurodegenerative disease characterized by loss of function and death of nerve cells in several areas of the brain leading to loss of cognitive function such as memory and language. "In a combined Alzheimer’s disease and control group, MAG:PLP1 was significantly reduced in BSIII–IV and BSV–VI compared to BS0–II." (PMID 33723589, 2021). "The MAG:PLP1 ratio was highly significantly reduced in Alzheimer’s disease and vascular dementia patients compared to age-matched controls." (PMID 33723589, 2021). "Two-way ANOVA revealed a highly significant interaction effect between infection and dementia status for MAG:PLP1 in both Alzheimer’s disease and vascular dementia patients." (PMID 33723589, 2021). "Here, we show that MAG:PLP1 and PDGFRβ were significantly reduced, at an early stage i.e. BSIII–IV, in Alzheimer’s disease indicating vascular dysfunction from an early to intermediate stage of disease." (PMID 33723589, 2021). "In all dementia cases (i.e. combining Alzheimer’s disease, mixed and vascular dementia) but not controls, MAG:PLP1 in the FC correlated positively with DBP (Pearson’s r = 0.1985, P = 0.0259, n = 126) and PC (r = 0.1971, P = 0.0282, n = 124) but not with SBP." (PMID 37113314, 2023). "One-way ANOVA, to assess differences between control and disease groups after stratification according to the presence of infection, showed MAG:PLP1 to be reduced in controls with infection to a level comparable to that in Alzheimer’s disease or vascular dementia patients without infection." (PMID 33723589, 2021). "White matter ACE activity did not correlate significantly with the MAG:PLP1 ratio and was similar in Alzheimer’s disease, vascular dementia and controls." (PMID 24618270, 2014). "Indeed, in cases with no or minimal Alzheimer’s disease pathology (BS0–II), MAG:PLP1 declined and VEGF and fibrinogen increased by magnitudes similar to those in end-stage Alzheimer’s disease in control donors with terminal infection." (PMID 33723589, 2021).
AL amyloidosis (7 papers, 2022 to 2025). AL Amyloidosis is a plasma cell disorder characterized by the aggregation and deposition of insoluble amyloid fibrils derived from misfolding of monoclonal immunoglobulin light chains usually produced by a plasma cell tumor. "Anti-MAG and light-chain amyloidosis can cause painful sensory neuropathy, often accompanied by autonomic features, whereas POEMS syndrome can result in axonal, demyelinating, or mixed neuropathy." (PMID 40940747, 2025). "This includes anti-MAG neuropathy, POEMS (polyneuropathy, organomegaly, endocrinopathy, M protein, skin changes) syndrome, and immunoglobulin light-chain amyloidosis, all of which exhibit characteristics of paraneoplastic disorders." (PMID 40940747, 2025).
depression (7 papers, 2022 to 2025). "The increase in a LIF expression mediated by EF-2001 affected the levels of the myelin proteins such as MBP (myelin-based protein) and MAG (myelin-associated glycoprotein) and alleviated the depression symptoms by the enhancement of the NF-κB p65/LIF/STAT3 pathway." (PMID 38397099, 2024). "Decreased levels of MAG, MAL, CNPase, and MOBP, were also confirmed in animal models of depression and in the human postmortem study in depressed patients." (PMID 38235150, 2023). "Emerging evidence has shown that myelination-related transcriptional genes that are important for myelin structure (CNP, MAG, MOG) are significantly downregulated in patients with major depressive disorder (Aston, Jiang and Sokolov, 2005)." (PMID 35959443, 2022).
Stroke (7 papers, 2016 to 2023). Sudden impairment of blood flow to a part of the brain due to occlusion or rupture of an artery to the brain. "By encouraging axonal growth and counteracting the inhibition induced by myelin-associated glycoprotein (MAG), this medication has the potential to enhance the outcomes for patients who have suffered a stroke." (PMID 36678774, 2022). "The current study builds on these findings, providing evidence that GSK249320, an anti-MAG monoclonal antibody, initiated IV 24 hours after stroke onset enters the ipsilesional hemisphere and is associated with a small effect on functional outcomes." (PMID 28018988, 2016). "When the CNS is acutely injured by either trauma or stroke, myelin and oligodendrocyte associated neurite growth inhibitors, such as Nogo-A and myelin-associated glycoprotein (MAG), are released into the CNS environment and inhibit neuron, particularly axon, regeneration." (PMID 27738345, 2017). "TAT-PEP, a recombinant protein consisting of PirB extracellular motif fused with TAT, which demonstrated the ability to rescue neurite outgrowth inhibition induced by Nogo, MAG and OMgp in stroke, was used to treat PC12PirB." (PMID 28676756, 2017). "MAG expression increases after stroke, further increasing the potential importance of this molecule as a therapeutic target." (PMID 28018988, 2016). "After stroke, MAG expression increases, further highlighting the potential to target post-stroke molecular events in order to promote neuroplasticity." (PMID 28018988, 2016). "GSK249320 is a monoclonal antibody that neutralizes MAG-mediated inhibition and so may promote axon outgrowth and improve post-stroke outcomes." (PMID 28018988, 2016). "The current study tested the hypothesis that GSK249320, an anti-MAG monoclonal antibody, when initiated 24 hours or later after induction of an experimental stroke in rodents, would be an effective restorative therapy, improving long-term behavioural outcomes without modifying infarct volume." (PMID 28018988, 2016).
Ataxia (6 papers, 2012 to 2025). Ataxia refers to impaired coordination of voluntary muscle movement. "Findings associated with anti-MAG antibodies more typical for the paediatric population include ataxia after chicken pox and their presence in 70% of patients diagnosed with autism." (PMID 35624969, 2022). "Our findings thus suggest that this variant causes protein loss-of-function and associate MAG variants with ataxia with oculomotor apraxia (AOA)." (PMID 32340215, 2020). "We identified a novel missense variant in MAG (c.124T>C; p.Cys42Arg) in homozygosity, in a consanguineous family presenting with cerebellar ataxia." (PMID 32340215, 2020). "Therefore, MAG variants should be considered in the diagnosis of hereditary cerebellar ataxia with oculomotor apraxia, in addition to spastic paraplegia." (PMID 32340215, 2020). "Homozygous variants in MAG, encoding the myelin-associated glycoprotein (MAG), have been associated with a complex neurological syndrome, including spastic paraplegia type 75 (SPG75), progressive neuropathy, ataxia and prominent sensorial dysfunction." (PMID 32340215, 2020). "Consistently, the recovery of tremors and the decreasing of periaxonal vacuoles in the dop1a-null-mutant rats, as well as the recovery of nystagmus/ataxia in IV-2, both indicated that there might be other pathways that could complement the dysmyelinogenesis of PLP/MAG partially in adulthood." (PMID 38818041, 2024).
autism (6 papers, 2012 to 2022). Persistent deficits in social interaction and communication and interaction as well as a markedly restricted repertoire of activity and interest as well as repetitive patterns of behavior. "This may also involve dysfunction of myelination pathways, as shown by the finding of circulating antibodies against myelin basic protein (MBP) and myelin-associated glycoprotein (MAG) in some autism patients." (PMID 25126406, 2014). "In the present work, patients with severe autism had significantly higher serum anti-MAG auto-antibodies than children with mild to moderate autism, P < 0.001." (PMID 22898564, 2012). "Patients with severe autism had significantly higher serum anti-MAG auto-antibodies than children with mild to moderate autism, P < 0.001." (PMID 22898564, 2012). "In this study, we have tried to find a possible link between the reduced serum levels of 25-hydroxy vitamin D and the elevated serum levels of anti-MAG auto-antibodies in autism." (PMID 22898564, 2012). "In addition, children with severe autism had significantly higher frequency of seropositivity of anti-MAG auto-antibodies (90.6%) than autistic patients with mild to moderate autism (33.3%), P < 0.001." (PMID 22898564, 2012). "Thus, anti-MAG auto-antibodies might be playing a role in the pathogenesis of brain damage, the extent of which may determine the clinical severity of autism." (PMID 22898564, 2012). "The higher levels of MAP-2, NFP, MBP, MAG, α-synuclein S100B and GFAP (3.2 to 4.8-fold) autoantibodies reported in ASD children warrant further research for developing autoantibodies screening as a biomarker for detection of early autism." (PMID 31035713, 2019).
demyelinating disease (6 papers, 2018 to 2025). A broad group of disorders that affect the myelin sheaths that cover the neurons. "Inflammatory responses against MBP, MOG and MAG are known to cause demyelinating diseases." (PMID 32000863, 2020). "Myelin-associated glycoprotein (MAG) and myelin oligodendrocyte glycoprotein (MOG) are glycoproteins found in myelin, with MOG often being a target for autoimmune responses in demyelinating diseases." (PMID 39081666, 2024).